PIK3CA (phosphatidylinositol-4,5-bisphosphate 3-kinase catalytic subunit alpha)
Diseases named in the same sentence as PIK3CA in open-access papers (continued):
Sharing a sentence is not in itself a finding about the gene and the disease.
tumor (continued). "Favorable SCC growth conditions are mediated by the presence of tumor- or stromal-derived growth factors as well as activating mutations in signaling pathways such as PIK3CA or inactivation of the signaling inhibitor PTEN." (PMID 35196980, 2022). "Another drug targeting PIK3CA mutation directly, Alpelisib has proved its anti-tumor efficacy with endocrine therapy in ER + MBC with PIK3CA mutations." (PMID 36029565, 2022). "We found numerically more RFI events at 5 years in patients with SHR-positive, HER2-negative and PIK3CA-mutated tumours than in patients with PIK3CA-wildtype tumours (7.9% and 6.0%, resp.)." (PMID 36279023, 2022). "GINS1, a proliferative subtype (24%~34%), is endowed with elevated proliferative activity, high tumor purity, immune-desert, and PIK3CA mutations." (PMID 36345721, 2022). "This study described an OCCC case that presented with a PIK3CA mutation and was successfully managed with careful and complete resection of the tumor." (PMID 36123851, 2022). "This patient with mutation of the PIK3CA gene was sensitive to platinum-based chemotherapy, showed a significant downwards trend in tumor markers, and was in good health within the year of follow-up." (PMID 36123851, 2022). "According to genomic datasets derived from 123 CRC tumor specimens in this study, the number of PIK3CA and DNMT3A mutations was significantly increased in patients aged over 65 years (p = 0.032 and 0.039, respectively)." (PMID 35203549, 2022). "NCCN Guidelines for invasive breast cancer (version 2.2022) recommend assessment for PIK3CA mutations in tumour tissue or ctDNA in this setting." (PMID 35347327, 2022). "Up to 30% of TNBC tumours harbour aberrations in the oncogenic PI3K/AKT pathway through mutation of either AKT serine/threonine kinase 1 (AKT1) or PIK3CA." (PMID 36176752, 2022). "For example, it was observed that several resistant tumours harbouring PIK3CA mutations affected the therapeutic efficacy of anti-MAPK drugs." (PMID 35335966, 2022). "Three out of eight patients with a PIK3CA mutated tumor, were treated with the ATH regimen: one patient obtained pCR; two patients did not." (PMID 35740668, 2022). "Six pools of “classical” CTCs were investigated for molecular characterization, but none of them showed the PIK3CA p.(Glu542Lys) mutation, the primary PIK3CA mutation found as a hallmark of tumor tissue." (PMID 35682999, 2022). "Here, we show that CYH33 exhibits a manageable safety profile and preliminary anti-tumor efficacy in solid tumors harboring PIK3CA mutations." (PMID 36385120, 2022). "We next compared the results obtained from each technology to evaluate their analytical performance and their capability of detecting PIK3CA mutations both in primary tumor and metastasis samples." (PMID 36428975, 2022). "Conversely, the activating PIK3CA mutations and increase in pAKT were abrogated by AR inhibition, which gave an exposition of the tumor-promoting action of AR." (PMID 35847875, 2022). "In summary, this study described an OCCC case that presented with a PIK3CA mutation and was successfully managed with careful and complete tumor resection." (PMID 36123851, 2022).
tumor (continued). "Right-sided disease has previously been shown to be associated with higher rates of tumor immune infiltration, MMRd disease (19.2%), and PIK3CA mutations (18.4%) all of which were noted to be enriched in our post-transplant CRC population." (PMID 36661655, 2022). "Patient 160, despite having the lowest clonal diversity in the entire cohort (i.e. 3 clones identified amongst the three tumor samples profiled), had two independent PIK3CA mutations, including PIK3CAQ546K in A1 and PIK3CAE545K in A2 and A3." (PMID 35642016, 2022). "The pooled HR for cancer-related death considering PIK3CA-mutated tumours was calculated as 0.74 (95% CI: 0.56–0.97) with a heterogeneity of I2 = 0% (tau2 = 0, Q = 3.99, p = 0.41)." (PMID 35171329, 2022). "Regarding samples, PIK3CA mutational status can vary among primary tumor and metastases, as for the HR and the HER2 expression." (PMID 36579519, 2022). "Many other clinical and histopathological factors have been related to pCR, and the predictive role of biomarkers, such as the 21-gene assay, PIK3CA mutation, Ki-67 index, and tumor-infiltrating lymphocytes, is being evaluated." (PMID 36551746, 2022). "This testing identified an expanded pathway-altered subgroup of FAKTION participants whose tumours carried a PIK3CA mutation or AKT1 E17K or deleterious PTEN alteration, as well as the corresponding expanded pathway non-altered subgroup." (PMID 35671774, 2022). "Tumor gene activation mutations (such as PIK3CA, AKT, and mTOR) are closely related to cancer growth and therapeutic drug resistance." (PMID 36452344, 2022). "Either tumor tissue or plasma ctDNA can be collected for PIK3CA mutation testing, but fresh, paraffin‐embedded tumor tissue is preferred." (PMID 38089455, 2022). "Tumours defined as the LAR subtype typically contain a higher number of PIK3CA mutations, and the pCR rate following NACT is significantly lower compared to other subtypes." (PMID 36003779, 2022). "Specific knockdown of PIK3CA inhibited proliferation, migration, anchorage-independent growth and in vivo tumour growth of cells with PIK3CA mutations." (PMID 35317488, 2022). "Meanwhile, we investigated the concomitant genomic alterations of PIK3CA mutations, analyzed the tumor driver genes and their enriched pathways, and screened for genes that can be used as drug targets." (PMID 35778737, 2022). "While BRAFV600E mutations have a very high frequency in both PTC and ATC tumours (59.7% and 45%, respectively), mutational changes in PIK3CA are only present in 0.5% of PTC patient samples and at a much higher frequency of 18% in ATC." (PMID 35193694, 2022). "Tumor growth can be triggered by activating mutations in PIK3CA (Phosphatidylinositol-4,5-Bisphosphate 3-Kinase Catalytic Subunit Alpha) and poor expression of tumour suppressor genes (such as PTEN)." (PMID 36578543, 2022). "The ultra-sensitive detection of tumor-specific mutations (E542K and E545K) and ctDNA methylation of PIK3CA gene were performed using a coupled plasma model based on local surface plasmon resonance (LSPR) and gold nanoparticles (AuNPs)." (PMID 36005048, 2022). "In consonance with our findings, previous studies have reported that PIK3CA mutation promotes tumor progression partly by enhancing glycolysis." (PMID 34980012, 2022). "The treatment groups were also balanced for the proportion of participants whose tumours carried PIK3CA mutations versus AKT1 mutations versus PTEN alterations." (PMID 35671774, 2022).
tumor (continued). "In the present study, two genetic mutations (KRAS + PIK3CA) were sufficient to induce LGSOC tumor growth and progression in nude mice." (PMID 35326657, 2022). "Tumor-derived PIK3CA mutations are clustered in two hotspots: one in the helical domain at E542, E545, Q546, and the other in the kinase domain at the H1047 site." (PMID 35418124, 2022). "The targeted technique, referring to ddPCR or beads amplification magnetics PCR (BEAMing-PCR), is applied to detect previously determined tumor-specific mutations, such as PIK3CA and ESR1." (PMID 35565189, 2022). "No false-positive result was detected and the mutations in exfoliated cells were observed only in cases showing mutations in corresponding tumours, giving a specificity of 100% for both PIK3CA and AKT1 genes." (PMID 35317488, 2022). "Subsequently, the PI3K pathway was implicated in tumorigenesis with somatic mutations in PIK3CA genes found in several tumor types." (PMID 36046843, 2022). "In total, at least one PIK3CA mutation was identified in 19 tumor samples from patients (59% frequency), and 7 tumor samples from patients (20%) had at least one pathogenic mutation in PIK3CA." (PMID 35330454, 2022). "The combined targeted DNA and RNA sequencing revealed an activating mutation in PIK3CA in the tumor tissue." (PMID 35154272, 2022). "The SOLAR-1 trial showed that PIK3CA mutations, detected either using ctDNA or in tumor tissue, were predictive of improved PFS for alpelisib plus fulvestrant." (PMID 36046843, 2022). "These PIK3CA-mutated BCs have been shown to be susceptible to therapy with alpelisib in preclinical tumor models and clinical trials in association with fulvestrant." (PMID 35682999, 2022). "present a strategy for ultrasensitive detection of tumor-specific mutations (E542K and E545K) and methylation of ctDNA of the PIK3CA gene based on localized surface plasmon resonance (LSPR) and the coupling plasmon mode of gold nanoparticles (AuNPs)." (PMID 36568152, 2022). "High concordance of HER2 amplification between baseline ctDNA and tumour tissue has been demonstrated, and the co-presence of baseline PIK3CA/R1/C3 or ERBB2/4 mutations in ctDNA were associated with poor PFS." (PMID 35954487, 2022). "Concerning MBC, the US Food and Drug Administration approved both alpelisib and a companion diagnostic test (therascreen PIK3CA RGQ PCR Kit, Qiagen, Chatsworth, CA, USA) to detect PIK3CA mutations in tumor and/or plasma samples." (PMID 35122700, 2022). "PIK3CA-mutations were significantly more frequent in well and intermediately compared to poorly differentiated tumours (G1, OR 3.13, 95% CI 1.970–4.986; G2, OR 2.14, 95% CI 1.478–3.085)." (PMID 36279023, 2022). "Complete and partial responses to BRAF inhibition have also been observed in patients with complete loss of PTEN tumor expression and with PIK3CA tumor-associated activating mutations." (PMID 34680615, 2021). "While PIK3CA mutations are relatively rare events in each tumor type, a number of unique alterations have emerged as contributing to aberrant signaling." (PMID 33669749, 2021). "Among the relevant findings of the gbmSYGNAL network, the network revealed modulation of IRF1 by mutated NF1 and PIK3CA to increase tumor lymphocyte infiltration." (PMID 33801334, 2021). "In this trial, prospectively collected serial tumour and blood samples were analysed for PIK3CA and other mutations." (PMID 33799597, 2021).
tumor (continued). "It has been previously shown that approximately 13% of all the PIK3CA mutations correspond to multiple variants occurring in the same tumor." (PMID 34287479, 2021). "Retrospective analyses in this study showed that patients with a PIK3CA mutation detected in ctDNA benefit more from addition of alpelisib compared to all patients in which PIK3CA mutations were detected in tumor tissue (primary tumor or metastasis)." (PMID 33920135, 2021). "Binary logistic regression analysis showed that the stage (p = 0.018), tumor size (p = 0.039), and PIK3CA mutation in circulating DNA collected before treatment (p = 0.035), were significantly associated with survival." (PMID 34203201, 2021). "This variant was further detected in the tumor sample from a different anatomic site (left ovary) in addition to PIK3CA and ARID1A variants previously identified in the tumor from the right ovary." (PMID 34660321, 2021). "Circulating tumor cells (CTC) have been also investigated as a possible source of biologic materials for the detection of PIK3CA mutations." (PMID 33842357, 2021). "A high‐throughput PIK3CA mutations‐barcoding screen was performed to reveal impactful mutation sites in tumour growth and drug responses." (PMID 34842356, 2021). "Mutations deregulating the PI3K pathway are also common in the endometrioid OC; around 20% of cases harbor PTEN tumor suppressor gene mutations and around 30% display activating PIK3CA mutations." (PMID 35052761, 2021). "The skin metastasis sample showed a very similar pattern of alterations in driver genes as compared with the treated tumor, including the PIK3CA hotspot mutation, the amplifications in CCND1, EGFR, and FGFR3, and the deletions in CDK1B, CDKN2A, and CDKN2B." (PMID 34680239, 2021). "The additional macrodissection showed that in three of the four OCCC cases with PIK3CA mutation in the tumor, the additional sample had the same hotspot mutation as the original sample (cases a, b, and d)." (PMID 34172890, 2021). "In the FUSCC cohort, we found PIK3CA mutations were like to enriched in the metastatic HR‐HER2+ tumours which were exposed with long‐term trastuzumab‐based treatment via the analysis of variant allele fraction (VAF) (p = .0078)." (PMID 34842356, 2021). "Mutations in the PIK3CA gene can affect tumor cell proliferation, metastasis, and patients' survival." (PMID 34367282, 2021). "Nevertheless, only the tumor cells containing the PIK3CA mutation spread beyond the brain barrier, relocated in different organs, and then aggressively expanded in the immunosuppressed recipients." (PMID 34301805, 2021). "We noted that in six of seven (85.7%) cases with recurrence, there was a PIK3CA mutation detected in tumor tissue DNA or circulating cfDNA collected before the recurrence occurred clinically." (PMID 34203201, 2021). "Using pooled PIK3CA mutation screens, we revealed the contributions of various PIK3CA alleles to tumour growth and drug responses, providing the evolutionary therapeutics to overcome anti‐HER2 resistance." (PMID 34842356, 2021). "Testing for PIK3CA mutation is typically done on tumor tissue, preferably a recent site of metastases to ensure accurate results." (PMID 34609096, 2021). "The PIK3CA-mutated HBCx-86 model responded to the combination by exhibiting remarkable tumor regression." (PMID 34020697, 2021).
tumor (continued). "Among the 14 patients with PIK3CA tumour mutations at diagnosis, 3/14 (21.4%) achieved a pCR after neoadjuvant chemotherapy, and 2/14 (14.3%) were non-responders." (PMID 34911971, 2021). "A logical interpretation is that sequential mutation of GATA3 facilitates acquisition of invasive characteristics following PIK3CA mutations to promote tumor initiation." (PMID 33795819, 2021). "As for BELLE studies, tumor PIK3CA mutation status was found to be a predictive factor of response for PFS4." (PMID 34453076, 2021). "In the present study, we detected a pathogenic variant in the PIK3CA gene correlated with tumor recurrence." (PMID 34680380, 2021). "PIK3CA mutation tumor cells showed poor sensitivity to first-line chemotherapy in vitro and in vivo." (PMID 33237662, 2021). "In contrast, alpelisib has been recommended in the situation of activating mutation of PIK3CA in the tumor." (PMID 33530335, 2021). "The six patients with a PIK3CA mutation detected in their archival tumour had the corresponding PIK3CA mutation detected in their pre-treatment plasma ctDNA (at 920–31,300 copies/mL plasma) and in all on-treatment ctDNA samples." (PMID 33799597, 2021). "A tumor sample from one patient, who harbored an E545D mutation in PIK3CA, showed partial pathological response to CRT, but the patient did not take aspirin." (PMID 33430037, 2021). "The SOLAR-1 trial is analyzing the efficacy of alpelisib on tumor harboring activating PIK3CA mutations and can already show a benefit for such patients, which led to the approval of alpelisib and the therascreen PIK3CA RGQ PCR kit by the FDA." (PMID 34885114, 2021). "According to the previous reports, over 80% of somatic, activating PIK3CA mutations in solid cancers and benign overgrowth disorders cluster at three residues, two glutamic acids (E) residues at codons 542 and 545, and a histidine (H) residue at codon 1047." (PMID 34074347, 2021). "The factors significantly correlated to recurrence included PIK3CA mutation in circulating DNA collected during follow-up and tumor size (p = 0.0114 and p = 0.0185, respectively) while late stage was marginally associated with recurrence (p = 0.0561)." (PMID 34203201, 2021). "The best response achieved was stable disease in nine (75%) participants at eight weeks and confirmed stable disease at 16 weeks in six (50%) of these, one of whom had a PIK3CA E542 mutation in archival tumour." (PMID 33799597, 2021). "Reinforcing the importance of the R1021 mutant for class I PI3K regulation is the fact that mutation of the equivalent R992 in PIK3CA to either Leu or Asn has been found in tumour samples." (PMID 33661099, 2021). "An inferior survival after relapse for the panitumumab treated patients was observed, especially for the population with a mutation (either KRAS, BRAF, NRAS or PIK3CA), possibly due to accelerated tumour growth caused by the anti-EGFR therapy." (PMID 34253874, 2021). "In five cases (5.6%), PIK3CA mutations were only found in plasma; in ten cases (11.2%), PIK3CA mutations were only found in the tumor tissue." (PMID 34453076, 2021). "Further analysis indicated that lower m6Sig score also correlated with greater tumor mutation loads, PD-L1 expression, and higher mutation rates in SMGs (e.g., PIK3CA and SMAD4)." (PMID 33500720, 2021). "In the preclinical and clinical settings, PIK3CA mutations are now more and more often considered a biomarker of tumor sensitivity/resistance to specific treatments, including paclitaxel, trastuzumab, and endocrine treatment." (PMID 34281208, 2021).